LINC00305 (long independently transcribed non-coding RNA 305)
Synonyms: C18orf20; NCRNA00305; MGC39571; HsT1235
Gene: Long non-coding RNA gene on chromosome 18 (64,079,989 to 64,153,377, reverse strand). Ensembl gene ENSG00000179676.
Subcellular location: Secreted
Diseases named in the same sentence as LINC00305 in open-access papers:
LINC00305 is named in the same sentence as 4 diseases in open-access papers, as found by Europe PMC text mining. Sharing a sentence is not in itself a finding about the gene and the disease. The quoted sentences say what the papers report.
atherosclerosis (2 papers, 2017 to 2018). A disease characterized by the build-up of fatty material and calcium deposition in the arterial wall resulting in partial or complete occlusion of the arterial lumen. "In the present study, we analysed the established GWAS atherosclerosis database and found that LINC00305, which contains putative causal atherosclerosis-associated SNP, is a potential regulator of atherosclerosis." (PMID 28393844, 2017). "Increased LINC00305 expression was also detected in the peripheral blood mononuclear cells (PBMC) from atherosclerosis patients compared with that from normal controls." (PMID 28393844, 2017). "The functional role of LINC00305 in the development of atherosclerosis in patients as well as the mechanisms by which the SNP variations affect LINC00305 expression remain important questions that merit further investigation." (PMID 28393844, 2017). "The specific enrichment of LINC00305 in atherosclerotic cells and tissue further supports an active role of LINC00305 in the development of atherosclerosis." (PMID 28393844, 2017). "Together, these results indicate a potential role of LINC00305 in the development of atherosclerosis." (PMID 28393844, 2017). "LINC00305 expression is enriched in atherosclerotic plaques as well as in PBMCs of atherosclerosis patients, and is upregulated in LPS-stimulated THP-1 cells." (PMID 28393844, 2017). "We observed significantly enhanced LINC00305 expression in atherosclerotic plaques as well as in the PBMCs of atherosclerosis patients, and showed that LINC00305 primarily expressed in monocytes." (PMID 28393844, 2017). "Together, these results support the hypothesis that LINC00305 expression plays an important role in the progression of atherosclerosis." (PMID 28393844, 2017). "LINC00305 upregulates the expression of genes encoding pro-inflammatory cytokines in THP-1 cells and enhances HASMC phenotypic switching, phenomena that are critical to the development of atherosclerosis." (PMID 28393844, 2017). "LINC00305 promotes an interaction between the membrane protein lipocalin-interacting membrane receptor (LIMR) and the inflammatory gene aryl hydrocarbon receptor repressor (AHRR) via activation of the NF-kappaB pathway in human monocytes, further contributing to the development of atherosclerosis." (PMID 30523422, 2018).
rheumatoid arthritis (1 paper, 2020). A chronic, systemic autoimmune disorder characterized by inflammation in the synovial membranes and articular surfaces. "Increased expression of LINC00305 was also observed in serum of rheumatoid arthritis (RA) patients." (PMID 33329688, 2020).
LINC00305 also shares sentences with these, for which no sentence is quoted: endothelial dysfunction (2 papers); testicular germ cell tumor (1).